TMEM150A (transmembrane protein 150A)
Description:
Regulates localization of phosphatidylinositol 4-kinase (PI4K) to the plasma membrane, possibly by reducing the association of TTC7 (TTC7A or TTC7B) with the PI4K complex. Acts as a regulator of phosphatidylinositol 4-phosphate (PtdIns(4)P) synthesis. May also play a role in fasting-induced catabolism (By similarity).
Synonyms: TMEM150; DRAM5; TM6P1; FLJ90024; TTN1
Tractability: Antibody: UniProt places it where antibodies can reach, with high confidence; its Gene Ontology location is reachable by antibodies, with high confidence; UniProt predicts a signal peptide or a membrane-spanning region.
Gene: Protein-coding gene on chromosome 2 (85,598,547 to 85,603,201, reverse strand). Ensembl gene ENSG00000168890.
Subcellular location: Cell membrane
Gene Ontology:
Molecular function: protein binding
Biological process: phosphatidylinositol phosphate biosynthetic process; protein localization to plasma membrane
Cellular component: plasma membrane
Genetic constraint (gnomAD): Loss-of-function variants: 18 observed, 31.51 expected, observed/expected ratio (o/e) 0.57, 90% interval 0.39 to 0.85. The upper end of that interval is the gene's LOEUF score, 0.85, which puts it in group 3 of 6, group 1 being the genes least tolerant of losing a copy. Missense variants: 251 observed, 369.25 expected, observed/expected ratio (o/e) 0.68, 90% interval 0.61 to 0.75. Synonymous variants: 127 observed, 149.72 expected, observed/expected ratio (o/e) 0.85, 90% interval 0.73 to 0.98.
Homologues: Orthologues: chimpanzee TMEM150A (100% identical), macaque TMEM150A (99% identical), guinea pig TMEM150A (94% identical), rat Tmem150a (92% identical), mouse Tmem150a (92% identical), dog TMEM150A (91% identical), pig TMEM150A (89% identical), rabbit TMEM150A (69% identical), zebrafish tmem150aa (69% identical), zebrafish tmem150ab (69% identical), tropical clawed frog tmem150a (55% identical), Caenorhabditis elegans F11E6.6 (19% identical). Paralogues in human: TMEM150B (29% identical), TMEM150C (23% identical), DRAM2 (21% identical), DRAM1 (21% identical).
Diseases named in the same sentence as TMEM150A in open-access papers:
TMEM150A is named in the same sentence as 9 diseases in open-access papers, as found by Europe PMC text mining. Sharing a sentence is not in itself a finding about the gene and the disease. The quoted sentences say what the papers report.
breast carcinoma (2 papers, 2022). "We first determined that TMEM150C/DRAM4 and TMEM150A/DRAM5 are significantly expressed in different breast cancer cell lines, with MDA-MB-157 cells expressing a high level of both TMEM150C/DRAM4 and TMEM150A/DRAM5." (PMID 40396042, 2022). "According to their expression in breast cancer cell lines and their function in cell survival, generating mice knocked out for Tmem150c/Dram4 and/or Tmem150a/Dram5 would be beneficial to evaluate the impact of both genes in breast cancer in vivo, and potentially in other diseases." (PMID 40396042, 2022).
hepatitis C (1 paper, 2020). "Increased Tmem150A has been described as an antiviral response in endoplasmic reticulum (ER) permeability to hepatitis C viral replication." (PMID 32911797, 2020).
osteosarcoma (1 paper, 2022). A usually aggressive malignant bone-forming mesenchymal neoplasm, predominantly affecting adolescents and young adults. "To assess the role of TMEM150C/DRAM4 and/or TMEM150A/DRAM5 in modulating autophagy, we overexpressed either TMEM150C/DRAM4 or TMEM150A/DRAM5 in a human osteosarcoma cell line (Saos2), which expresses an average level of TMEM150C/DRAM4 and TMEM150A/DRAM5 mRNA." (PMID 40396042, 2022).
tumor (2 papers, 2022 to 2023). "Additionally, the TIMER database revealed a significant correlation between TMEM150A overexpression and the levels of tumour purity, CD4+ T cells, and DCs." (PMID 38055673, 2023).
cancer (1 paper, 2023). A tumor composed of atypical neoplastic, often pleomorphic cells that invade other tissues. "Furthermore, prognostic nomograms related to TMEM150A expression were associated with the prognosis of patients with cancer." (PMID 38055673, 2023).
TMEM150A also shares sentences with these, for which no sentence is quoted: Alzheimer disease (1 paper); genetic diseases (1); glioblastoma multiforme (1); influenza (1).